IL5 (interleukin 5)
Diseases named in the same sentence as IL5 in open-access papers (continued):
Sharing a sentence is not in itself a finding about the gene and the disease.
asthma (continued). "Several direct links between those major compounds and the inhibition of the GATA-3/Th2 responses have been reported; for example, Camellia japonica oil suppressed asthma occurrence through the GATA-3, IL-4, and IL-5 pathways and its effective and major component is oleic acid." (PMID 30823378, 2019). "IL-5 levels were significantly lower in the P+S coculture both in the children with and without asthma." (PMID 31673233, 2019). "MSCs appeared to exert an anti-IL-5 effect on the in vitro culture in both the children with and without asthma." (PMID 31673233, 2019). "Firstly, these findings indicate that remodeling is present even in mild asthma, and it is driven to some degree by eosinophil-derived TGF-beta 1; secondly, anti-IL-5 can prevent this process by regulating the TGF-beta-enhanced deposition of matrix proteins through the reduction of eosinophils." (PMID 31480806, 2019). "In addition, focusing only on the taxa that were shown to be significantly decreased within the asthma BALs, their combined relative abundance inversely correlated with BAL IL-5, IFN-γ, and IL-15 levels (n = 40)." (PMID 31836714, 2019). "In spite of the consistent effect of anti-IL-5 in the reduction of blood eosinophils, the lack of a favorable effect in clinical asthma outcomes was obvious." (PMID 31480806, 2019). "Asthma pathogenesis primarily involves activation of eosinophils and CD4+ T cells, with downstream inflammation mediated mainly by Th2-type cytokines (IL-3, IL-4, IL-5, IL-9, IL-13, and granulocyte macrophage colony-stimulating factor)." (PMID 30126769, 2019). "We suspect that such asthma patients are not IL-5-positive patients with CRSwNP/ECRS but are SE-IgE-positive patients." (PMID 31606052, 2019). "Increased levels of IL5 and IL13 found in MPP children may be connected to the concurrence of MPP and asthma in children." (PMID 31780733, 2019). "Interleukin 5 (IL-5) is a cytokine produced by limited types of cells, such as CD4+ T cells, innate lymphocytes type 2 (ILC-2), mast cells, and eosinophils, which are all involved in the airway inflammation of asthma." (PMID 30498762, 2018). "Though IL-5 and IL-13 secretion tended to be higher in those with asthma than in healthy subjects, these differences were not statistically significant." (PMID 30174671, 2018). "Many studies determined the effect of IL4, IL5 and IL13 in asthma pathogenesis there for making balance between TH1 and TH2 cytokines might be helpful in asthma management." (PMID 29743896, 2018). "While data suggest the possibility of an immunogenic response to anti-IL-5 mAbs, the potential clinical implications in patients with asthma are not yet firmly established." (PMID 30115042, 2018). "In the present study, we demonstrated that tiotropium bromide improved bronchoconstriction, and that it significantly reduced the concentrations of IL-5, IL-6, IL-13, and KC/CXCL1 in BALF, and subsequently led to reduced neutrophilic airway inflammation in a mouse model of OVA-induced asthma." (PMID 29882826, 2018). "In our experiment, Treg cells isolated from patients with asthma expressed higher levels of Th2-type cytokines, such as IL-4, IL-5, and IL-13, rather than IFN-γ, the Th1-type cytokine." (PMID 30013989, 2018). "Mepolizumab is not the only anti-interleukin-5 antibody under investigation for improving asthma control." (PMID 30701170, 2018). "In addition to previously identified variables, the data provide further evidence for the importance of IL-2, IL-5, IL-6, IL-8, IL-10, IFN-γ, TNF, asthma, polyposis, and aspirin sensitivity, in efforts to demarcate distinct endotypes of CRS." (PMID 30283438, 2018). "We did not analyze Th2 cytokines, such as IL-4, IL-5, or IL-13, and therefore we cannot exclude a certain involvement of Th2 response in the regulation of blood coagulation in asthma." (PMID 28429138, 2017).
asthma (continued). "In mouse asthma models that use ovalbumin, house dust mite (HDM), papain, and fungal allergens, ILC2s uniformly increase in number and are the major source of IL-5 or/and IL-13, especially in the early phases of the disease." (PMID 28271447, 2017). "To date, trials of the efficacy of monoclonal antibodies that target either IL-5 or its receptor have not been undertaken in children with severe asthma, but given the prevalence of airway eosinophilia in children, this seems an obvious avenue to pursue." (PMID 28725641, 2017). "Although histologic or radiographic endpoints have not been systematically assessed in asthma, anti-IL-5 is effective in patients with severe, steroid refractory asthma and can be steroid sparing in patients with HES." (PMID 28831387, 2017). "The levels of inflammatory factors (IL-5, IL-6, IL-13, and TNF-α) and those of fibrosis-related proteins (basic fibroblast growth factor (bFGF), IGFBP-3, and TGF-β) were significantly higher in asthma patients than in healthy controls." (PMID 28796252, 2017). "The primary inflammatory lesion of asthma is accompanied by the accumulation of cluster of differentiation 4+ (CD4+) Th2 cells and Eos’s in the airway mucosa and its secretion of a series of cytokines, mostly IL-4, IL-13, IL-5, and IL-9." (PMID 28678189, 2017). "Immunoreactivity of Th2-derived cytokines (IL-4, IL-5 and IL-13) was only weakly detected in the epithelium of nasal biopsy specimens of non-severe asthma patients with CRS (respectively)." (PMID 28199345, 2017). "Interestingly, transdermal administration of NPRA siRNA nanoparticles significantly reduced eosinophilia, lung histopathology, pro-inflammatory cytokines IL-4 and IL-5, and AHR in an OVA-induced mouse asthma model." (PMID 28106744, 2017). "Extracts of Siegesbeckia glabrescens, a traditional medicinal plant in Korea, reduced mucus overproduction in airways in a asthma murine model, decreased the expression of iNOS and COX-2, reducing the number of inflammatory cells in BALF and the cytokine release (IL-4, IL-5 and IL-13)." (PMID 27445433, 2016). "Our findings with VVHE suggest that the V. vinifera fruits could act in asthma via its neutralizing effects on TH2 derived pro-inflammatory (TNF and IL-1β) and inflammatory (IL-4 and IL-5) cytokines, key elements in the pathophysiology of bronchial asthma." (PMID 27536321, 2016). "Airway inflammation is a key component of asthma and of the OVA-sensitization model and is characterized by the presence of granulocytes and increased levels of Th2 cytokines such as IL13, IL4 and IL5." (PMID 27820848, 2016). "The Th2 cytokines (IL-5) and regulatory T cytokine (Treg, IL-10) were also elevated in patients with asthma and allergic rhinitis but not atopic dermatitis in this study." (PMID 27918476, 2016). "Therefore, while other factors in addition to Th2 cells/cytokines are involved in the pathogenesis of asthma, it appears that WGP is specific in targeting the production of IL-4, IL-5, IL-13 and resulting eosinophilia in this model." (PMID 27390655, 2016). "Similarly, exposure to acute stressful life events in the context of chronic family stress has been linked to greater Th2 cytokine production, including levels of IL-4, IL-5, and IFN-gamma, among youth with asthma." (PMID 27965775, 2016). "Additionally in a comparable study in 40 children with asthma, we found that EBC acidity and IL-5 assessed every 2 months were significantly related to the exacerbation rate." (PMID 27049850, 2016). "IL-5 regulates the development, activation, migration, and survival of eosinophils and stimulates the expression of IL-6, which is a T- and B-cell growth factor that produces IgE and regulates CD4+ T-cell function to induce asthma." (PMID 25658604, 2015).
asthma (continued). "The sputum inflammatory mediator profiles were distinct with increased TH2 (IL-5, IL-13, and CCL26) and TH1 mediators (CXCL10 and 11) in severe asthma compared with COPD and increased IL-6, CCL2, CCL3, and CCL4 in COPD compared with severe asthma." (PMID 25129678, 2015). "In summary, HDAC2 gene expression and enzyme activity might be suppressed in patientswith asthma, resulting in NF-κB activation and increased BAL levels of IL-8, IL-5,IL-13, GM-CSF, and TNF-α." (PMID 25923460, 2015). "Expression of IL‐5 and IL‐13 was significantly higher among children with asthma, wheeze or mite sensitization compared to those without these features (P < 0.001)." (PMID 26061524, 2015). "In the development of asthma, allergen-specific CD4+ T cells play a pivotal role by facilitating airway inflammation, which is largely mediated by type 2 T-helper (Th2) cytokines such as interleukin 4 (IL-4), IL-5 and IL-13." (PMID 26488300, 2015). "In the current analysis, higher IL‐10 or IFN‐γ was only associated with asthma in the context of high IL‐5 and IL‐13 productions; children who produced IL‐10 but no IL‐5 (Class 1), or IFN‐γ but no IL‐5 (Class 2) were not at increased risk of asthma." (PMID 26061524, 2015). "Th2-type cytokines, including IL-4, IL-5, IL-13, IL-17, and IL-33 produced by activated CD4+ T-cells, enhance IgE production, eosinophil accumulation, and play a central role in the pathogenesis of asthma." (PMID 26385707, 2015). "In this study IL-5 was only detectable in 29% of the sputum samples collected during asthma exacerbation and no significant change in IL-5 during the course of asthma exacerbation was found." (PMID 25799487, 2015). "Additionally, not only the infiltration of neutrophils and eosinophils but also the levels of IL‐4, IL‐5, and IL‐13 were reduced upon bvPLA2 treatment in OVA‐induced asthma mice." (PMID 26734460, 2015). "This implicates IL-5-induced airways eosinophilia as a negative regulator of TLR7 expression and antiviral responses, which provides a molecular mechanism underpinning the effect of eosinophil-targeting treatments for the prevention of asthma exacerbations." (PMID 26108570, 2015). "The ongoing anti-IL5 clinical trials, show promise of a safe, effective treatment option for the severe ‘eosinophilic’ asthma endotype independent of their atopic status." (PMID 25709744, 2014). "Absence of Th2 cytokines IL4, IL-5 and IL-13 was also detected in school children (median age 12 years) with severe treatment-resistant asthma regardless of bronchial eosinophilia." (PMID 25905006, 2014). "Nevertheless, no study has explored the effects of such IL-5 mAbs in asthma exacerbations in obese individuals." (PMID 24204674, 2013). "The Th2 cytokines IL-4 and IL-13 also seem to play a role in asthmatic inflammation, but therapies targeting IL-5, IL-4, or IL-13 have provided little or no relief of asthma symptoms and little relief from airways hyperresponsiveness." (PMID 23150736, 2012). "In summary, administration of SCTE in this mouse asthma model significantly decreased the number of eosinophils in BALF and lung tissue, and reduced IL-4 IL-5, IL-13, TNF-α, and eotaxin production in BALF and total IgE and OVA-specific IgE levels in plasma after OVA challenge." (PMID 23244755, 2012). "Th2 cytokines, IL-4, IL-5 and IL-13 produced by activated CD4+ T cells, play a central role in the pathogenesis of asthma by controlling the key process of immunoglobulin E (IgE) production, growth of mast cells and the differentiation and activation of mast cells and eosinophils." (PMID 22514638, 2012). "In the GCE-induced asthma model, intranasal administration of GCE increased airway hyperresponsiveness (AHR), inflammatory cell infiltration, productions of serum immunoglobulin E, interleukin (IL)-5, IL-13 and TNF-α production in alveolar macrophages." (PMID 23094102, 2012).
asthma (continued). "Additionally, oral administration of ScLL reduced IL-4 and IL-5 levels in murine models of acute and chronic inflammation and lead to increased IFN-γ and IL-10 production in asthma inflammatory model, directing a shift from Th2- to Th1-biased immune response." (PMID 23107170, 2012). "The role of eosinophils in asthma has been under scrutiny since clinical trials showing that anti-IL-5 therapy did not improve the disease symptoms for allergic asthmatics albeit eosinophil numbers were reduced." (PMID 21235798, 2011). "Airway eosinophilia, together with Th2 cytokines IL-4, IL-5 and IL-13, may ultimately contribute to AHR in asthma." (PMID 21695271, 2011). "Besides, some studies have suggested the probable contribution to asthma pathogenesis of CD8+ T-cells producing IL4 and IL5 (type 2 CD8+ T-cells) in the lungs and blood of asthmatic individuals." (PMID 22047167, 2011). "CD4+ T helper type 2 (TH2) cells, their cytokines IL-4, IL-5 and IL-13 and the transcription factor STAT6 are known to regulate various features of asthma including lung inflammation, mucus production and airway hyperreactivity and also drive alternative activation of macrophages (AAM)." (PMID 22014099, 2011). "The finding that systemic levels of IL-12 (p40), IL-5, and IFNγ/IL-5 reflect the regulatory differences between the allergic and non-allergic pediatric asthma subgroups, led us to address this issue more closely." (PMID 21179211, 2010). "CBMC proliferation and cytokine (IL-5 and IFN-γ) responses, and age 5 PBMC proliferation responses, were compared to anti-cockroach, anti-mouse, and anti-dust mite IgE levels, wheeze, cough, eczema and asthma." (PMID 20684781, 2010). "Despite these promising results, the clinical approaches towards asthma therapy by neutralizing IL-4, IL-5, or IL-13 frustrated the high expectations or did not progress to clinical trials." (PMID 20976014, 2010). "In an animal model of asthma a single application of this STAT1 decoy oligonucleotides significantly reduces airway hyperresponsiveness, the number of BAL eosinophils and lymphocytes and the BAL level of IL-5." (PMID 18315837, 2008). "Current concepts of asthma pathobiology strongly suggest that these factors contribute to asthma symptoms and stimulate secretion of asthma-producing TH2 cytokines (IL-5 and eotaxin) into BAL." (PMID 19057703, 2008). "In an animal model of asthma there is increased IL-19 expression and transfer of the IL-19 gene into healthy mice up-regulated IL-4 and IL-5, but not IL-13, however, IL-19 up-regulated IL-13 in “asthmatic” mice." (PMID 18315837, 2008). "Given the central role of IL-5 in eosinophilia this provides further evidence that SEB may at least, play some role in allergic diseases such as AEDS and asthma." (PMID 16952309, 2006). "After the FESS, the levels of specific IgE, IL-4 and IL-5 were attenuated significantly in CRS-asthma patients, but not in asthma alone patients." (PMID 16677400, 2006). "The dissociation of GCH from airway eosinophilia has been well documented in murine asthma models, in which anti-IL-5 (TRFK-5), or IL-5 deficiency reduced airway eosinophilia without affecting the induction of GCH." (PMID 15829015, 2005). "Similarly, the preventive activities of RosA in female BALB/c mice induced asthma demonstrated that pretreatment with RosA (5–20 mg/kg) 1 h prior to the OVA challenge significantly inhibited increases in Th2 cytokines (IL‐4, IL‐5, and IL‐13) and markedly reduced IgE concentrations in the BALF." (PMID 41523289, 2026). "This case suggests that chronic airflow limitation in severe asthma is not always irreversible and that switching to tezepelumab may induce dramatic functional recovery even after anti-IL-5 therapy." (PMID 41853402, 2026).
asthma (continued). "Asthma accompanied by Type 2 inflammation primarily involves the stimulation of Th2 cells and Type 2 innate lymphoid cells (ILC2) in response to allergens and viruses, leading to the secretion of Type 2 cytokines including IL‐4, IL‐13, and IL‐5 (interleukin‐5)." (PMID 41568067, 2026). "This is supported by recent evidence indicating that dupilumab provides comparable, if not superior, improvements in asthma control test (ACT) scores compared with intraclass switching following inadequate response to anti-IL-5 or anti-IL-5R monoclonal antibodies." (PMID 41149833, 2025). "However, in the context of a respiratory disease such as asthma, bronchial IL-5 levels increase and blood levels do not reflect that found in the airways." (PMID 40943268, 2025). "Its levels seemingly do not vary with anti-IL-5 (mepolizumab) or anti-IL-5R (benralizumab) therapy, although some variability has been reported, despite no apparent consequence on functional and asthma control parameters." (PMID 40649123, 2025). "While specific IL-5-targeting agents have failed to achieve meaningful improvement in AD, they have been shown to reduce eosinophil counts and ameliorate allergic rhinitis symptoms in asthma." (PMID 40869144, 2025). "By mitigating airway hyperreactivity, reducing the levels of inflammatory cytokines (IL-4, IL-5 and IL-13) involved in the Th2 immune response, and enhancing Treg immune regulation (IL-10 and TGF-β1), hydrogen therapy has emerged as a promising adjunct strategy in asthma management." (PMID 41146240, 2025). "Similarly, increases in classic asthma-driving cytokines were modest (IL-4, IL-5) or absent (IL-13)." (PMID 39229121, 2025). "However, the levels of IFN-γ, IL-10, and type-2 cytokines, including IL-4, IL-5, and IL-13, were not significantly different between Sema3E KO and WT mice in the type-2 low asthma model." (PMID 40512736, 2025). "Although anti-IL-5 and anti-IL-5Rα agents did not reduce FeNO in all patients with severe asthma, recent evidence suggested that anti-IL-5 agents can reduce FeNO levels, and that responders to the agents were more likely to achieve clinical remission after 12 months." (PMID 41584312, 2025). "Moreover, in a murine model of asthma, CBD-X administration significantly downregulated key asthma markers such as IgE and pro-asthmatic cytokines IL-4, IL-5, and IL-13 in both blood and lung tissues, and inhibited the migration of leukocytes, eosinophils, and neutrophils to lung tissues." (PMID 39459021, 2024). "Similarly, in a study involving patients with asthma, the administration of nemiralisib did not yield statistically significant reductions in sputum IL-5, IL-13, IL-6 or IL-8 compared to placebo." (PMID 39427187, 2024). "Finally, inhibition of aerobic glycolysis could not only reduce the production of lactate, IL-5, IL-17, and IFN-γ, but also stimulate that of IL-10 and Foxp3 in a mouse model of asthma." (PMID 39040099, 2024). "The two forms of asthma phenotypes are type 2-low, characterized by non-eosinophilic inflammation, neutrophilic involvement, metabolic responses, and type 2-high IL-5 and IL-13, which are primarily eosinophilic and pathologically driven by Th2 cells that produce IL-4." (PMID 39594470, 2024). "This could allow iEos to endotype severe asthma patients, pointing out candidates for biological therapy with anti-IL-5/IL-5R agents even though they do not have a high eosinophil count in peripheral blood." (PMID 39886455, 2024). "These anti-IL-5 drugs have not yet been used clinically for asthma treatment in China." (PMID 38308249, 2024). "In addition, histamine is found to promote IL‐10 and inhibit TGF‐α in OVA‐induced asthma in mice, thereby reducing the total number of cells in bronchoalveolar lavage fluid (BALF) and the number of inflammatory factors such as IL‐4, IL‐5, and IL‐13 in lung tissue." (PMID 38687096, 2024).